ZNF106 (zinc finger protein 106)
Description:
RNA-binding protein. Specifically binds to 5'-GGGGCC-3' sequence repeats in RNA. Essential for maintenance of peripheral motor neuron and skeletal muscle function. Required for normal expression and/or alternative splicing of a number of genes in spinal cord and skeletal muscle, including the neurite outgrowth inhibitor RTN4. Also contributes to normal mitochondrial respiratory function in motor neurons, via an unknown mechanism.
Synonyms: SH3BP3; ZFP106; ZNF474
Tractability: PROTAC: UniProt records ubiquitination sites on it; ubiquitination databases record sites on it.
Gene: Protein-coding gene on chromosome 15 (42,412,823 to 42,491,141, reverse strand). Ensembl gene ENSG00000103994.
Subcellular location: Nucleus, nucleolus; Nucleus speckle
Subcellular location (Human Protein Atlas): Nucleoli; Cytosol; Nucleoplasm
Gene Ontology:
Molecular function: protein binding; RNA binding
Cellular component: nuclear speck; nucleolus
Genetic constraint (gnomAD): Loss-of-function variants: 63 observed, 192.73 expected, observed/expected ratio (o/e) 0.33, 90% interval 0.27 to 0.4. The upper end of that interval is the gene's LOEUF score, 0.4, which puts it in group 1 of 6, group 1 being the genes least tolerant of losing a copy. Missense variants: 2,088 observed, 2,389.7 expected, observed/expected ratio (o/e) 0.87, 90% interval 0.84 to 0.91. Synonymous variants: 776 observed, 854.75 expected, observed/expected ratio (o/e) 0.91, 90% interval 0.86 to 0.96.
Homologues: Orthologues: chimpanzee ZNF106 (98% identical), macaque ZNF106 (96% identical), dog ZNF106 (90% identical), pig ZNF106 (89% identical), rabbit ZNF106 (87% identical), guinea pig ZNF106 (82% identical), rat Zfp106 (78% identical), mouse Zfp106 (77% identical), tropical clawed frog znf106 (47% identical), zebrafish znf106a (35% identical), zebrafish znf106b (6% identical).
Diseases named in the same sentence as ZNF106 in open-access papers:
ZNF106 is named in the same sentence as 24 diseases in open-access papers, as found by Europe PMC text mining. Sharing a sentence is not in itself a finding about the gene and the disease. The quoted sentences say what the papers report.
Bladder Cancer (2 papers, 2022 to 2023). "We found that mRNA level of 106 was significantly reduced in ESCA tissues, this was similar to the reported results that ZNF106 expression was downregulated and associated with a good predictive value in Bladder Cancer." (PMID 37013470, 2023). "For rs146381257 (ZNF106), frequencies were increased in prostate cancer (33.3%), lung cancer (28.6%), breast cancer (28.6%), lymphoid neoplasms (23.8%), urinary bladder cancer (19.0%), pancreatic cancer (14.3%), and kidney cancer (14.3%)." (PMID 36199081, 2022). "Although germline variation in ZNF106 has not previously been associated with cancer risk, a recent study found it to be associated with worse urinary bladder cancer survival." (PMID 36199081, 2022).
cognitive decline (1 paper, 2024). "Furthermore, additional studies on the link between human brain aging or aging-related cognitive decline and changes in the expression of ASPHD2, BAD, CRTAP, IPW, and ZNF106 which remain elusive, may also be advantageous." (PMID 38428408, 2024).
esophageal cancer (1 paper, 2023). A primary or metastatic malignant neoplasm involving the esophagus. "Results indicate that ZNF91, and ZNF586 were upregulated in esophageal cancer tissue than adjacent tissue, whereas ZNF502, ZNF865, ZNF106, and ZNF225 was downregulated." (PMID 37013470, 2023).
invasive breast carcinoma (1 paper, 2019). A carcinoma that infiltrates the breast parenchyma. "Overexpression of DCAF13, DNMT3B, KPNA2, EXO1, FANCI, RACGAP1, and ZNF106 in invasive breast carcinoma patients showed poor survival, while overexpression of CDKN2A, SORBS1, and TP63 showed better survival." (PMID 32010179, 2019).
cancer (3 papers, 2017 to 2022). A tumor composed of atypical neoplastic, often pleomorphic cells that invade other tissues. "Two of these variants were positively associated in our analysis of any 2+ primary cancers: rs555607708 (CHEK2; OR [95% CI] = 1.57 [1.09, 2.25], p = 0.015) and rs146381257 (ZNF106; OR [95% CI] = 5.38 [1.07, 27.18], p = 0.042)." (PMID 36199081, 2022). "Results showed that the “zinc finger protein 106,” which is involved in the insulin receptor signalling pathway, was the main activated upstream in cancer (p value = 2.9E − 06, z-score = 2.0)." (PMID 31827511, 2019).
ZNF106 also shares sentences with these, for which no sentence is quoted: amyotrophic lateral sclerosis (2 papers); lung carcinoma (2); acute pancreatitis (1); breast carcinoma (1); cervical cancer (1); dyslipidemia (1); Hypertension (1); kidney cancer (1); leukaemia (1); lymphoid neoplasm (1); melanoma (1); metabolic disorders (1); motor neuron degeneration (1); Multiple Organ Failure (1); neurodegenerative disease (1); Obesity (1); pancreatic cancer (1); prostate carcinoma (1); type 2 diabetes (1).